BDNF (brain derived neurotrophic factor)
Diseases named in the same sentence as BDNF in open-access papers (continued):
Sharing a sentence is not in itself a finding about the gene and the disease.
Cognitive impairment (continued). "BDNF is the potential serum biomarker of ALS with the C9orf72 mutation, while the C9orf72 repeat expansion elevates the risk of cognitive impairment in ALS and ALS‐FTD." (PMID 40099804, 2025). "In nude mice, which are deficient in functional T cells, lower levels of brain‐derived neurotrophic factor (BDNF) and cognitive deficits, including poor performance in the MWM task, have been observed." (PMID 40717391, 2025). "SCO+HMM produced cognitive deficits through a notable decrease of BDNF levels relative to the control group (96.50 ± 6.344 vs. 258.3 ± 14.93 pg/ml/mg, respectively, p <0.0001)." (PMID 40325262, 2025). "Previous studies have shown that different models of periodontitis disrupt BDNF signaling in the hippocampus, contributing to depressive‐like behaviors and cognitive deficits." (PMID 41326981, 2025). "Several clinical investigations have documented an association between diminished levels of cerebrospinal fluid, plasma, and serum whole BDNF with HIV-related cognitive impairment, as evidenced by decreased performance in neurocognitive assessments." (PMID 39548055, 2025). "We also purposed to research the roles of ERK1/2, CREB, and BDNF pathways that regulate cognitive impairment." (PMID 40358798, 2025). "According to the GSEA phenotype analysis, APOE, BDNF, CACNA1A, COMT and UCHL1 were identified as the main genes associated with cognitive impairment (FDR q-value < 0.05)." (PMID 41301762, 2025). "AYAC both during and post-chemotherapy had higher rates of self-perceived and objective cognitive impairment, lower plasma BDNF, and elevated IL-4, IL-6, IL-8, IL-10, and IFN-γ compared to NC during follow-up." (PMID 40597835, 2025). "The paradoxical finding of elevated BDNF alongside cognitive impairment in a tumor-bearing model was proposed by the authors to originate from long-term activation of microglial cells rather than representing a beneficial neuroplastic response." (PMID 41155372, 2025). "This systematic review highlights consistent associations between increased pro-inflammatory cytokines (i.e., IL-6, IL-1β, TNF-α), reduced levels of hippocampal BDNF, and cognitive impairment in preclinical models of breast cancer and chemotherapy." (PMID 41155372, 2025). "Following PM2.5 exposure, these miRNAs exhibit differential changes in expression, thereby regulating BDNF to promote cognitive disorders and diseases." (PMID 39997934, 2025). "4.Further Investigation of Neurotrophic Factors: Altered BDNF expression in infected mice points to a role in cognitive deficits." (PMID 40977748, 2025). "Impairment in this circuitry due to reduced BDNF expression can exacerbate cognitive deficits in PD." (PMID 39940980, 2025). "Consistently, in APP/PSEN1 double‐mutant transgenic mice, an HF‐rTMS treatment (5 Hz) highlighted an improvement in learning, memory, and cognitive impairment also due to a specific modulation on the BDNF‐TrkB signaling pathway." (PMID 40530618, 2025). "We propose that RSV alleviates DOX-induced cognitive impairment in adult rats by promoting BDNF release, which involves activation of the CREB-ERK pathway, by suppressing oxidative stress and inflammation." (PMID 40358798, 2025). "Given this, our study sought to investigate how subchronic HgCl2 exposure interacts with type 2 diabetes to influence AChE activity and BDNF levels, potentially aggravating cognitive deficits." (PMID 40726602, 2025). "Evidence supports that high-frequency rTMS increases BDNF expression and improves task-specific cognitive deficits in PD patients." (PMID 39940980, 2025). "The study revealed that consuming omega-3 fatty acids after sepsis in rat brains helps to improve brain-derived neurotrophic factor (BDNF) levels in the hippocampus, reduces inflammatory mediators, and diminishes oxidative markers and cognitive impairment." (PMID 40416371, 2025). "Keywords used were: (“breast cancer” AND “cognitive impairment” AND (“brain derived neurotrophic factor” OR “cytokines”)." (PMID 41155372, 2025).
Cognitive impairment (continued). "Clearance of Tau restored BDNF/TrkB neurotrophic signaling, improved synaptic plasticity, and alleviated cognitive deficits." (PMID 40426267, 2025). "The authors also reported a parallel increase in mature BDNF protein levels in the prefrontal cortex, suggesting a possible neuroprotective action relevant to cognitive deficits in schizophrenia." (PMID 40141736, 2025). "Studies have reported that radiation exposure suppresses the CREB/BDNF signaling pathway, contributing to emotional disturbances and cognitive impairments." (PMID 40508105, 2025). "Studies have shown that chronic physical exercise increases peripheral levels of BDNF (plasma or serum) of healthy older adults as well as individuals with neuropsychiatric and metabolic diseases, such as mild cognitive impairment (MCI) and diabetes." (PMID 40869831, 2025). "More research is needed on hippo BDNF in learning, memory, and cognitive deficits related to SD with more behavioral methods." (PMID 39829139, 2025). "Reduced levels of BDNF have been observed in patients with neurodegenerative disorders, correlating with cognitive deficits and disease progression." (PMID 40892845, 2025). "Histone deacetylase six increases in AD brains, mainly in the hippocampus, leading to low BDNF-induced cognitive impairment." (PMID 40380033, 2025). "In recent years, both cytokines and BDNF have been proposed as potential biomarkers of cognitive impairment in a range of clinical populations, including individuals with Alzheimer’s disease, Parkinson’s disease and the elderly." (PMID 41155372, 2025). "In vivo, PE administration alleviated Aβ-induced cognitive deficits, which were associated with reduced expression of JNK, NF-κB, iNOS, and COX and increased CREB/BDNF signaling in the hippocampus." (PMID 40871065, 2025). "The supplementation effectively attenuated cognitive impairment and reversed the decline in BDNF and TrkB." (PMID 40430064, 2025). "Correlates with lower BDNF protein levels and poorer cognitive performance in schizophrenia patients, suggesting a role in cognitive impairment in schizophrenia." (PMID 40379790, 2025). "The treatment normalized hippocampal FNDC5/irisin expression, which was associated with a reduction in Aβ and P-tau proteins, improved BDNF and insulin signaling, and alleviated cognitive impairments." (PMID 40018518, 2025). "The central aim of our investigation was to assess cognitive impairment and to analyze the relationship between specific biomarkers - BDNF, BACE1, VEGF, GFAP and IL-1β and cognitive dysfunction in adults PWE." (PMID 40291844, 2025). "This includes three emerging trends: the impact of exercise on cognitive impairment in AD patients, the effects of exercise on brain-derived neurotrophic factor (BDNF) and Amyloid beta, and the influence of exercise on Stress and neuroinflammation." (PMID 40248333, 2025). "It was revealed that serum BDNF levels were reduced in the group of patients with cognitive impairments." (PMID 41562905, 2025). "Recent evidence also suggests that inhibition of the AhR/NF-κB/JNK axis activates BDNF/TrkB signaling, which attenuates the progression of CKD and the cognitive deficits associated with CKD." (PMID 40791659, 2025). "Babaei and coworkers employed a similar method for AD induction using the Aβl-42 peptide, which resulted in cognitive impairment, a decline in BDNF, NGF, and Bcl-2 levels, and an increase in Bax and caspase-3 expression." (PMID 40430064, 2025). "A33 restored the decreased phosphorylation and BDNF expression, reversing cognitive impairment in AlD mice." (PMID 39921664, 2025). "More recently it has been found in systematic reviews that BDNF increases or remains the same after exercise interventions in elderly people and varying results have been found in patients with Mild Cognitive Impairment and Alzheimer’s Disease." (PMID 40519238, 2025).
Cognitive impairment (continued). "BDNF activators, as for instance, TrkB agonists and TrkB mimetics, can restore the synaptic function and ameliorate cognitive deficits in neurodegenerative diseases." (PMID 41562905, 2025). "OLIG2 can significantly improve memory and cognitive impairment after transient ischemia by increasing oligodendrocyte-specific protein and brain-derived neurotrophic factor expression." (PMID 38221931, 2024). "Mediation analysis suggested that BDNF played a mediating role of 20-35% between cognitive impairment and skeletal muscle." (PMID 38559694, 2024). "have shown that acute nicotine treatment reduced LPS‐produced cognitive deficit through upregulating BDNF expression and decreasing neuroinflammation in rat hippocampus." (PMID 38353058, 2024). "BDNF is a protein related to cognitive impairment because it regulates synaptic plasticity and excitatory and inhibitory synaptic transmission." (PMID 38397422, 2024). "The administration of Lactobacillus restores microbial homeostasis and facilitates recovery from cognitive impairments by enhancing the BDNF/TrkB signaling pathway within cortical and hippocampal regions through gut-brain axis interactions." (PMID 38654189, 2024). "TREM2 has also been demonstrated to attenuate neuroinflammation and neurological damage via Akt/CREB/BDNF signaling as well as ameliorate cognitive impairment and anxiety in a mouse model of traumatic brain injury." (PMID 38956653, 2024). "Correlations have been established between BDNF concentrations and the severity of cognitive impairment." (PMID 38654189, 2024). "schizophrenia, a complex neuropsychiatric disorder characterized by cognitive deficits and adverse symptoms, has been another focus of interest in the context of BDNF." (PMID 39568824, 2024). "The early cognitive impairment seen in mice with sepsis is related to the sepsis-induced downregulation of BDNF expression in the hippocampus." (PMID 38827289, 2024). "This study demonstrated that the role of DEX in reducing SCOP-induced cognitive impairment is partially mediated by the increase in BDNF/TrkB/CREB signaling pathway activity." (PMID 39768379, 2024). "A positive correlation was found between BDNF levels and scores on the five RBANS indices, suggesting that diminished BDNF is associated with cognitive impairments in PD." (PMID 39935805, 2024). "A recent meta-analysis examined the effects of exercise on plasma BDNF levels in individuals with various neurodegenerative disorders, including multiple sclerosis, Parkinson’s disease, mild cognitive impairment (MCI), and Alzheimer’s disease." (PMID 39935805, 2024). "It affects dendritic spine regeneration, reduces BDNF levels, and induces cognitive impairment by disrupting the cytoskeleton, activating oxidative stress, and targeting reactive astrocytes." (PMID 39355779, 2024). "LGG supplementation mitigates sepsis-related cognitive impairment in mice and preserves BDNF expression and p-TrkB levels in the hippocampus." (PMID 38827289, 2024). "Taken together, these results indicate that FPF not only protects against oxidative stress but also increases BDNF expression, thereby ameliorating SD-induced cognitive impairment." (PMID 39683616, 2024). "Several studies have reported that the cognitive impairment induced by SD is related to a reduction in BDNF levels in the hippocampus." (PMID 39683616, 2024). "Propranolol treatment for 6 weeks at a dose of 5mg/kg reduced cognitive impairments and hippocampal β-amyloids and phospho-Tau protein levels and increased BDNF and Akt activity in diseased mice." (PMID 37966585, 2024). "In this respect, we evaluated the long-term effect of PRM and LCM, administered singly in a high-dose or in a low-dose combination of both on comorbid anxiety, cognitive impairment, BDNF, and Cyclin D1 hippocampal expression in an experimental model of TLE." (PMID 39727966, 2024).
Cognitive impairment (continued). "Experimental evidence from animal models suggests that butyrate can improve obesity-induced cognitive impairments by preventing quinolinic acid-induced BDNF reductions through inducing H3K18ac (acetylation of lysine 18 of histone H3) at BDNF promoters." (PMID 39770976, 2024). "In contrast, experimental studies reveal that some traditional ASMs like phenobarbital, topiramate, and lamotrigine can reduce mRNA levels of BDNF and lead to cognitive deficits." (PMID 39727966, 2024). "Occlusal support loss caused plastic changes in ascending nerve pathway and induced cognitive impairment in rats by down‐regulating BDNF and synaptic plasticity." (PMID 38898731, 2024). "On the other, high levels of BCAAs result in an increase in brain-derived neurotrophic factor, impaired spatial memory, and cognitive impairment." (PMID 38265552, 2024). "We investigated the precise role of brain‐derived neurotrophic factor (BDNF) in the cognitive impairments induced by repeated ketamine exposure during the neonatal period." (PMID 38332635, 2024). "Alterations in the BDNF/TrkB signaling pathway with aging, and pathological conditions are all potential mechanisms of cognitive impairment." (PMID 38827289, 2024). "LPS suppresses BDNF expression by upregulating NF-κB signaling, resulting in cognitive impairment with neuroinflammation." (PMID 39203872, 2024). "In animal models, low BDNF concentrations resulted in cognitive deficits due to disturbed neurotransmission and neuroplasticity." (PMID 39148705, 2024). "As well, ACEI captopril attenuates cognitive impairment in the experimental rats through augmentation of brain BDNF/TrkB signalling." (PMID 38899551, 2024). "Recent studies have shown that hippocampal BDNF levels are decreased in rodents with SCOP-induced cognitive impairment." (PMID 39768379, 2024). "The increased expression of BDNF, VEGF, and MAP2 in the DAI-T group supports the potential use of rTMS in treating cognitive impairments associated with DAI." (PMID 39051213, 2024). "Numerous studies have proposed that the reduction in brain-derived neurotrophic factor (BDNF) expression is another mechanism of SD-induced cognitive impairment." (PMID 39683616, 2024). "Our study has also proved that the increasing expression of BDNF secreted by microglia had ability to improve surgery-induced cognitive impairment." (PMID 38750371, 2024). "A dose-dependent relationship between cognitive impairment, BDNF concentration and As exposure in humans has been shown." (PMID 39324118, 2024). "Morris water maze tests were carried out to evaluate the cognitive impairment, while mRNA levels of neurotrophic factors (BDNF, NG) and neurodegenerative biomarker (VILIP‐1) in hippocampus were tested by q‐PCR." (PMID 38140846, 2024). "It restored the LPS-depleted brain-derived neurotrophic factor (BDNF) levels and reversed LPS-mediated cognitive impairment and behavioral disturbance." (PMID 38542359, 2024). "The cognitive impairment, axon demyelination, decreased BDNF, NG and increased VILIP‐1 expressions in hippocampus were all alleviated by exogenous exosome miR‐124‐3p." (PMID 38140846, 2024). "OVX and AD caused significant cognitive impairment (p < 0.001), up-regulated miR-134a (p < 0.001), down-regulated SIRT-1, CREB, and BDNF protein expression (p < 0.001), and decreased antioxidant marker levels (p < 0.001) compared to the sham group." (PMID 39061398, 2024). "The expression of BDNF also indicates the level of cognitive impairment, and this biomarker is reliable for acetaminophen neurotoxicity." (PMID 38250995, 2024). "Our results showed that sleep disturbance before surgery exacerbated microglial M1 polarization and microglial BDNF-TrkB signalling dysfunction induced by surgery, resulting in postoperative emotional changes and cognitive impairments." (PMID 38221533, 2024). "It was established that a reduction in serum BDNF level leads to cognitive impairment in human and rodent models of obesity." (PMID 40255947, 2024).
Cognitive impairment (continued). "A recent study reported that DEX alleviated cognitive impairment in hypoxic–ischemic neonatal rats by promoting hippocampal neurogenesis via the BDNF/TrkB/CREB signaling pathway." (PMID 39768379, 2024). "miR-206-3p antagomir injected into hippocampus ameliorates cognitive deficits by enhancing the level of BDNF." (PMID 39659569, 2024). "LGG supplementation mitigates sepsis-related cognitive impairment and preserves BDNF expression and p-TrkB levels in the hippocampus of mice with sepsis." (PMID 38827289, 2024). "Previously, we found that forced and voluntary exercise improves cognitive deficits and increases BDNF levels in the hippocampus of hypothyroid rats." (PMID 38988101, 2024). "The fact that beta-amyloid formation reduces BDNF shows that BDNF has the potential to be an effective pathway in correcting cognitive impairments such as dementia in Alzheimer’s disease." (PMID 39727960, 2024). "Our clinical studies of cancer patients undergoing chemotherapy found a correlation between pro-inflammatory signaling via TNFa, reduced plasma BDNF, and persistent cognitive impairments, pointing to a neuro-modulatory role of inflammation and BDNF." (PMID 39696694, 2024). "Our study indicated that rTMS notably ameliorated RIBI-induced cognitive disorders, by mitigating pyroptosis in microglia and promoting hippocampal neurogenesis via mediating BDNF pathway." (PMID 38570868, 2024). "Taken together, our study suggests that the activation of the BDNF/TrkB/CREB signaling pathway plays an important role in the treatment of SCOP-induced cognitive deficits." (PMID 39768379, 2024). "Ganoderic acid has been found to have the potential in mitigating cognitive impairment induced by 5-FU through the BDNF-TrkB-ERK-CREB axis." (PMID 38348396, 2024). "For example, a meta-analysis involving 514 individuals with mild cognitive impairment (MCI) demonstrated that physical activity led to increased BDNF and IGF-1 concentrations." (PMID 38961824, 2024). "BDNF downregulation mediates synaptic plasticity and excitability damage, leading to cognitive impairments in adulthood following repeated ketamine exposure during the neonatal period." (PMID 38332635, 2024). "Necrostatin-1 attenuated sevoflurane-induced cognitive impairment via brain-derived neurotrophic factor (BDNF)-tyrosine receptor kinase B (TrkB) signaling." (PMID 38994325, 2024). "In recent years, BDNF Val66Met polymorphism has been reported to interact with APOE ɛ4 on working memory, verbal and visual episodic memory, and the progression of mild cognitive impairment (MCI)." (PMID 38374884, 2024). "Another notifiable theory is the correlation between increased total cholesterol serum levels and increased brain-derived neurotrophic factor (BDNF) in the population of schizophrenic patients, which was found to play a role in cognitive impairment." (PMID 39061439, 2024). "Decreased BDNF levels correlate with cognitive deficits often seen in obese individuals, including impaired learning and memory, executive dysfunction, and mood disorders." (PMID 38785805, 2024). "Postoperative pain induced cognitive impairment, promoted axon demyelination, decreased BDNF, NG and increased VILIP‐1 expressions in hippocampus." (PMID 38140846, 2024). "Recent studies have shown that BDNF levels in plasma can be a predictor for cognitive impairment at very old age and in early stages of AD and dementia." (PMID 39199297, 2024). "The upregulation of GADD45γ within the hippocampal dentate gyrus contributes to adaptive responses by facilitating BDNF demethylation; conversely, downregulation of GADD45γ within the hippocampus leads to cognitive impairments and depressive-like behaviors." (PMID 38332860, 2024).